STAT1 (signal transducer and activator of transcription 1)
Diseases named in the same sentence as STAT1 in open-access papers (continued):
Sharing a sentence is not in itself a finding about the gene and the disease.
cancer (continued). "We could hypothesize that inflammatory responses observed in the middle and inner ear of our knockout mice could be due to enhanced expression of STAT3/STAT5 in absence of STAT1 as observed in cancer cells." (PMID 32991625, 2020). "KEGG pathway analysis further highlighted the role of S6K1 in cancer progression, in which the depletion of S6K1 could re-express a group of tumor suppressor genes including RASSF5, RASSF6, STAT1, CEACAM1, BNIP3L and SOCS2." (PMID 32201535, 2020). "Similarly, the extensive overlap among the Irf9, Stat1 and Nfyc regulons underscores their prevalent cofactorship and indicates that MC38-FUT9 cells display decreased expression of negative regulators of cancer stemness." (PMID 32927726, 2020). "Importantly, CIS requires the combined action of TNF and IFN-γ, as immune therapies of cancers in the absence of either IFN-γ, of Stat1- or of Tnfr1-signalling strongly accelerate the transformation and growth of cancer cells." (PMID 32165639, 2020). "Besides, IFN-γ could upregulate the expression of MHC I with the help of STAT1 signaling, pointing out another possible mechanism of IFN-γ to mediate cancer dormancy." (PMID 31297335, 2019). "As antigen presentation is dependent on STAT1 phosphorylation and it was previously shown that STAT1 nitration prevents STAT1 phosphorylation at amino acid position 7013,10, a novel mass spectrometry assay was developed to measure nitrated STAT1 in PBMC collected from patients with advanced cancer." (PMID 29133913, 2017). "In the cancer setting, it has been recently reported that EGFR downregulates the expression of APM components and HLA class I via activation of protein phosphatase type 11 (PTNP11) best known as SHP2 which dephosphorylates signal transducer and activator of transcription 1 (STAT1)." (PMID 28611673, 2017). "Therefore, a potential anti-cancer drug candidate should selectively inhibit STAT3 function as a transcription activator while not affecting STAT1 (and other STAT family members)." (PMID 23950841, 2013). "Stat1 and Stat5 might not be crucial for these cancers since phosphorylation of these two STAT members are not evident." (PMID 17311011, 2007). "Moreover, the addition of citrulline could restore the levels of total and phosphorylated STAT1 and PSMB9 proteins in response to IFNγ in ASS1-expressing cancer cells grown in an arginine-depleted medium, confirming the essentiality of arginine for the cancer cell response to IFNγ." (PMID 41511309, 2025). "The phosphorylation activation of Stat1 Ser727, rather than Tyr701, promotes ferroptosis through transcriptional inhibition of Nrf2 expression and highlights MgIG and GA as potential therapeutic approaches to enhance the safety of Crizotinib- based cancer therapy." (PMID 39160159, 2024). "The activation or overexpression of STAT1 could upregulate iNOS signaling pathways by promoting interferon regulatory factor 1 (IRF1) expression, resulting in the induction of inducible nitric oxide synthase (iNOS or NOS2), which, in turn, improved the effect of cisplatin on cancer cells." (PMID 38893499, 2024). "Overall, our findings identify that the phosphorylation activation of Stat1 Ser727, rather than Tyr701, promotes ferroptosis through transcriptional inhibition of Nrf2, and highlight MgIG and GA as potential therapeutic approaches to enhance the safety of Crizotinib-based cancer therapy." (PMID 39160159, 2024). "Moreover, unphosphorylated signal transducer and activator of transcription 1 (STAT1) may sustain the expression of interferon-stimulated genes (ISGs) that contribute to resistance to DNA damage, which may contribute to diminished response to cancer therapy." (PMID 38405101, 2024).
cancer (continued). "Furthermore, the phosphorylation of STAT1, a key transcription factor downstream of IFNβ pathway that contributes to the activation of IFN-stimulated genes, was also enhanced upon ATM inhibition in a panel of human and murine cancer cells (BT549, MDA-MB-231, H1299, H157, A549, B16-F10 and MC-38)." (PMID 36778120, 2023). "Thus, PRMTi specifically targets STAT1-high persisters rather than regrown STAT1-low cancer cells." (PMID 35089788, 2022). "Thus cancers with high expression of cytoplasmic STAT1 may have the potential and be “primed” for very strong STAT1 signaling, whereas cancers with low cytoplasmic STAT1 would not have that capability." (PMID 32275681, 2020). "Overall there was no consistent correlation between STAT1 and the four MSI diagnostic markers, which suggests that STAT1 may have value as an additional independent marker in further sub-classification of MSI cancers." (PMID 32275681, 2020). "In addition, many pro-apoptotic factors were lowly expressed, including those expressed at low levels in human HCC, such as TNFSF10, which induces apoptosis in cancer but not normal cells, and STAT1, which mediates the growth inhibition and apoptotic activities of IFN-γ." (PMID 28969016, 2017). "However, the regulation of signal transducer and activator of transcription-1 (STAT-3) was constitutively active and presented a slight down-regulation after the combination of IFN-γ and TNF-α treatment, which is consistent with others results in the cancer cells." (PMID 25811609, 2015). "Through the isolation of large EVs (LEVs) and classical exosomes from culture medium, we found p-STAT1 and p-STAT2 in LEVs, but not in classical exosomes, from USP5-depleted cancer cells after IFN-β treatment." (PMID 41321309, 2025). "The results indicated that, compared to adjacent non-cancerous tissues, the H-scores of CDK1, STAT1, COL1A2, and COL1A1 in cancer tissues were significantly elevated, with statistical significance (P < 0.05)." (PMID 39911265, 2025). "To selectively inactivate STAT3, we employed a cell screening model to identify the small molecule, CIB-6, which specifically inhibits STAT3 activation without affecting STAT1/2 and highlight the potential of using IFN in a combination anti-cancer therapy." (PMID 33805945, 2021). "Since STAT2 can form a complex with IRF9 and induce the expression of ISGs in the absence of STAT1, which seems to be tissue‐ and context‐dependent, we next silenced STAT2 in CAF1 before adding the CM from treated cancer cells." (PMID 33476079, 2021). "MET-amplified cancer cells showed highly phosphorylated JAK1/2 kinases, while STAT1 was poorly or not active." (PMID 30723303, 2019). "For STAT1 and MYC, data were available for MET and Non-Met cancers, but not for the non-cancer model." (PMID 24612742, 2014). "The role of STAT1 and STAT3 pathways in the production of CXCL5 in cancer has not been well studied." (PMID 24274066, 2013). "Beyond cancer, BRCC36 contributes significantly to non-oncological diseases; for example, it modulates inflammatory responses via regulation of NF-κB signaling and supports antiviral immunity by maintaining STAT1 stability." (PMID 41463377, 2025). "In this context, chronic DAMP-induced PRR/STING activation leads to persistent low-dose IFN-β autocrine and paracrine stimulation of cancer cells, which induces UISGF3-mediated transcription of the non-canonical pathway that overlaps with the IRDS (STAT1, ISG15) and includes RIG-I and MDA5." (PMID 35681561, 2022). "We found that IFN-γ significantly induced PD-L1 expression through activation of STAT1 signaling independent of autophagy levels in AGS and NCI-n87 cells, which is in accordance with others in several types of cancer." (PMID 30925913, 2019). "STAT1 expression was assessed by immunohistochemistry as described in Materials and methods through evaluation of the percentage of cells with nuclear STAT1 and cytoplasmic STAT1 in HPV-positive/negative cancer." (PMID 23708675, 2013).
cancer (continued). "To further investigate the connection between STAT1, STAT3 and said cytokines in drug resistance, we have treated cells (EP and LP) with cytokine-neutralized (IL-6, IL-10 and IL-1β) MDSC supernatant (in presence or absence of these cytokines), keeping untreated cancer cells as a control." (PMID 38304256, 2023).
bacterial infection (43 papers, 2007 to 2025). "STAT1 amorphic alleles cause severe viral and bacterial infections, while hypomorphic alleles cause mild disseminated mycobacterial disease." (PMID 40149454, 2025). "Recently, HECTD3 is implicated as an E3 ubiquitin ligase for TRAF3 and STAT1 in bacterial infection, hypothermic oxygenated perfusion of liver and cardiac inflammation models." (PMID 37402711, 2023). "STAT1 is crucial for the immune response against bacterial infection, and a decrease in its activity is linked to a higher bacterial infection susceptibility." (PMID 38098120, 2023). "In keeping with the noted antagonism between STAT1 and STAT3, STAT1-deficient mice were examined in our study for lung MDSC numbers as compared to wild-type mice after bacterial infection." (PMID 24066282, 2013). "Mice expressing STAT-1 with a mutation in the serine 727 site are extremely sensitive to bacterial infections and show a strongly reduced expression of IFNγ -induced genes." (PMID 23349666, 2013). "On the other hand, STAT-1 also plays an important role in bacterial clearance because mice expressing STAT-1 with a mutated 727 residue were shown to be highly sensitive to bacterial infections." (PMID 23349666, 2013). "Furthermore, our data underline the oppositional function of STAT1 for cell death regulation during bacterial infection." (PMID 34497340, 2022). "It has been previously shown that Stat1 Knockout (KO) mice are susceptible to mortality caused by viral and bacterial infection, primarily due to the fact that the STAT1 pathway is a major signaling pathway through which interferons (IFNs) mediate antiviral activity." (PMID 33022979, 2020). "Patients with complete STAT1 deficiency caused by null mutations have increased susceptibility to mycobacterial, viral, and bacterial infections, whereas biallelic hypomorphic mutations in AR partial STAT1 deficiency are associated with milder clinical severity." (PMID 28702025, 2017). "In our study, we also show an increase of STAT1 as a key regulator of monocyte differentiation, and STAT2 has been associated with dysregulation of macrophage phenotype during viral or bacterial infection." (PMID 37692050, 2023). "Patients with STAT1 GOF are also prone to bacterial infections; indeed, these were reported in 257 of the 442 patients." (PMID 33777053, 2021). "Recent studies from our laboratory demonstrated that STAT1 tyrosine phosphorylation is lower in NKLAM-/- than in WT mice upon bacterial infection." (PMID 31539400, 2019). "STAT1 makes an essential contribution to innate immunity against viral and intramacrophagic bacterial disease." (PMID 26882544, 2016). "In conclusion, our results show that the phosphorylation of STAT-1 serine 727 residue is prolonged in HLA-B27-expressing monocyte-macrophage U937 cells after bacterial infection." (PMID 23349666, 2013). "The viability of these pre-infected cells was evidenced by retention of tight junction integrity 24 h after ceasing bacterial infection as well as the ability of such cells to phosphorylate the STAT-1 transcriptional factor in response to cytokines." (PMID 17388785, 2007). "Genetic variants within STAT1 gene lead to loss-of-function (LOF) and gain-of-function (GOF) phenotypes, with a wide range of clinical presentations, including autoimmunity and life-threatening mycobacterial, severe viral, and bacterial infections." (PMID 40149454, 2025). "G. vaginalis and its supernatants can induce THP-1 macrophages to differentiate into the M1 phenotype, which is involved in defence against bacterial infections, elevated ROS levels, and stimulation of the NF-κB/STAT1 (Signal Transducer and Activator of Transcription 1) pathway." (PMID 38641803, 2024). "Co-binding of STAT1 and NFκB has been studied in the context of bacterial infection." (PMID 31231385, 2019).
bacterial infection (continued). "Inactivation of GSK3β by Akt-induced phosphorylation may result in activation of transcription factors during bacterial infection, including AP-1, STAT-1, STAT-3, and NF-κB." (PMID 29755479, 2018). "STAT3 and STAT1 are known to be up-regulated in cases of bacterial infection." (PMID 26220188, 2015). "Indeed, lung MDSC numbers almost doubled in STAT1−/− mice in response to bacterial infection with fewer neutrophils as compared to that in wild-type mice." (PMID 24066282, 2013). "Multi-omics alterations of Stat1 and Stat3 indicated their central role in the host immune response to P. aeruginosa infection, and their downstream molecules may be potential targets against bacterial infections and inflammatory diseases." (PMID 37643174, 2023). "In response to bacterial infection, the immunogenic genes, STAT 1 (signal transducer and activator of transcription 1), ISG 15 (interferon stimulating gene), and Mx “myxovirus resistance gene”, were shown to be elevated." (PMID 36611649, 2022). "SOCS1 and SOCS3 are target genes of STAT1 and STAT3, respectively, and are critical negative regulators of JAK-STAT signaling and thus maintain normal cytokine levels during viral or bacterial infections." (PMID 33968006, 2021). "These cells lack functional STAT1, have defective IFN responses, and therefore limit the spurious activation of ISGs during bacterial infection." (PMID 28002492, 2016). "Notably, we found that mTORC1 regulates the development of CD3+CD4-1+IFN-γ+ T cells in tilapia during intracellular bacterial infection at least by promoting the proliferation of CD3+CD4+ T cells and expression of the transcription factors STAT1 and T-bet." (PMID 36282845, 2022). "STAT1 is largely restricted to mediating the effects of IFNs, animals that lack STAT1 are exquisitely sensitive to microbial infections; while STAT3 mediates the effects of IL-6 and other gp130 ligands, and regulates the host response to bacterial infection." (PMID 33361763, 2020). "Murine strains lacking STAT1, a key protein involved in type 1 and type 2 interferon signaling networks, have been shown to be sensitive to a wide-number of viral and bacterial infections, including infections with MPXV." (PMID 28763036, 2017). "In addition, a further 12 ISGs of 380 tested ISGs including STAT1, STAT2, JAK1, IRF9, IRF2, IRF7 are key elements of IFN signaling, and classical and well-known ISGs such as ISG15, PKR, MX1, IFIT1, PML, IFI27 play key roles in viral or bacterial infections." (PMID 30717477, 2019).
cardiovascular diseases (14 papers, 2009 to 2025). "Some of the master regulators identified in WAT in the present study (Jun, Fos, Rarα, Pparα, Stat1, Stat5, Sp1) were also reported to control liver lipid metabolism and/or the inflammatory responses of the liver in experimental diet-induced cardiovascular disease." (PMID 24086498, 2013). "The Signal Transducers and Activators of Transcription (STATs) family is composed of 7 isoforms (STAT1; 2; 3; 4; 5A; 5B and 6) with STAT3 being the most important one in cardiovascular diseases." (PMID 21951574, 2011). "Antagonism between the STAT1 and STAT3 pathways is well described, notably in cardiovascular diseases, but reciprocal regulation between STAT1 and STAT6 is an emerging field, and our results may be reflecting such a phenomenon mediated by HDL with regard to macrophage inflammatory state." (PMID 23991225, 2013).
infectious disease (14 papers, 2012 to 2025). A disorder directly resulting from the presence and activity of a microbial, viral, or parasitic agent in humans. "STAT1 deficiency in mice and its loss-of-function mutations in humans have been causally linked to diverse infectious diseases." (PMID 26299368, 2015). "Mutations in the STAT1 gene leading to its reduced activity are associated with infectious disease." (PMID 25264875, 2014). "Studies in gene-modified mice and with cells from human patients suffering from recurrent infectious disease have unequivocally established the central importance of Stat1 for the establishment of protective innate immunity to viral and nonviral pathogens." (PMID 22719255, 2012). "The activation of STAT1 inhibits angiogenesis, which may be involved in the inflammatory process of thrombosis in infectious diseases." (PMID 35711689, 2022). "As part of the NIH/NIAID Animal Models of Infectious Diseases Contract, we further characterized the virulence and pathogenicity of wild-type filoviruses in mice lacking the cytoplasmic signal transducer and activator of transcription-1 protein (STAT-1 KO)." (PMID 34372594, 2021). "Many genes in the KLHDC7B-downregulated dataset are related, such as STAT1, IFIT3, and MX1, with the antimicrobial or infectious disease properties showing decreased expression." (PMID 30150751, 2018).
inflammation (13 papers, 2017 to 2026). Aberrant reaction of the microcirculation characterized by movement of fluid and leukocytes from the blood into extravascular tissues. "In the previous study, inhibition of STAT1-attenuated allergen-induced airway inflammation, particularly eosinophilic inflammation, which is closely associated with PGD2 dysregulation." (PMID 29255467, 2017). "Our previous studies found that IKKε mediated LSS-induced endothelial inflammation by activating STAT1 and Akt/IRF3 pathways." (PMID 38315275, 2024). "It is well known that IFN-γ induces macrophage differentiation into the M1 phenotype via the JAK/STAT1 signaling pathway and is involved in the pathogenesis of chronic inflammation and autoimmune diseases." (PMID 36510278, 2022). "The severity of airway inflammation was also exemplified by the presence of lymphoid cell aggregations or BALTs in allergen-challenged WT and Stat1−/− mice." (PMID 34755542, 2021). "However, since pY-STAT3 regulates inflammatory responses, both by blocking IFNγ induced STAT1 and IL-6 induced NFκB, inhibiting pYSTAT3 exacerbated cardiac inflammation." (PMID 36844399, 2023). "Here, we demonstrate that both type I and II IFN-induced STAT1 activation drives murine TLR9-induced systemic, and in particular, liver inflammation." (PMID 41561071, 2026). "This study investigates the unexplored role of STAT1, a transcription factor in pathogen-driven immune responses, in mediating TLR9-induced liver inflammation." (PMID 41561071, 2026). "The production of lung fibroblast-derived CX3CL1 were obviously reduced by specific inhibitors of the STAT-1 transcription factor, supporting the hypothesis that lung fibroblasts are an important cellular source of CX3CL1 and may contribute to causing pulmonary inflammation and fibrosis." (PMID 30884802, 2019).